SPON2 (spondin 2)
Diseases named in the same sentence as SPON2 in open-access papers (continued):
Sharing a sentence is not in itself a finding about the gene and the disease.
tumor (continued). "By multivariate analysis, SPON2 mRNA (P = 0.012), tumor grade (P = 0.001), and sarcomatoid (P < 0.001) could be recognized as an independent indicator for RFS of patients with localized ccRCC after nephrectomy." (PMID 32952742, 2020). "Additionally, tumor burden weight of SPON2 knockdown group was found to be significantly reduced compared to the control group." (PMID 32492954, 2020). "Furthermore, SPON2 silencing was observed to decrease cell proliferation and motility and reduce tumor growth in xenograft mice." (PMID 32492954, 2020). "SPON2 was also tested as a biomarker in plasma of CRC patients, where it was upregulated and downregulated after surgery was performed, indicating SPON2 to be associated with tumor burden." (PMID 30175151, 2018). "The spondin-2 correlated with tumor progression in many malignancies." (PMID 28060752, 2017). "Spondin-2 staining mainly located in cytoplasm of tumor cells." (PMID 28060752, 2017). "In addition, the impact of SPON2 on tumor progression, metastasis, differentiation, and patterns and its use as biomarker for prognosis linked to pulmonary ADC patient survival is not yet clear." (PMID 28938639, 2017). "However, the mechanism by which SPON2 regulates the accumulation of TAMs in the tumor microenvironment (TME) of CRC is unknown." (PMID 34583750, 2021). "Moreover, SPON2 silencing was observed to decrease tumor growth in xenograft mouse models." (PMID 32492954, 2020). "Spondin 2 (SPON2), a member of the Mindin F‐Spondin family, identifies pathogens, activates congenital immunity and promotes the growth and adhesion of neurons as well as binding to their receptors, but its role in promoting or inhibiting tumour metastasis is controversial." (PMID 31691494, 2020). "Previous studies have shown that SPON2 activates NF-κB signaling to facilitate EMT and enhance tumor progression." (PMID 40730813, 2025). "Our findings thus place SPON2 within a signaling context that connects inflammation, EMT, and angiogenesis, reinforcing its role in promoting an aggressive tumor phenotype." (PMID 40730813, 2025). "A bar plot illustrates the relative expression levels of SPON2 and MSMB in tumor versus normal samples, highlighting SPON2 as the most strongly upregulated marker in this cohort." (PMID 41200187, 2025). "Mechanistically, SPON2 activates the NF-κB/VEGF signaling axis to drive both macrophage polarization and EMT, thereby promoting tumor progression." (PMID 40730813, 2025). "On the contrary, SPON2 in HCC TME promoted the infiltration of M1 macrophages and inhibited tumor metastasis." (PMID 38542388, 2024). "Tumor exosomal HOTAIRM1 can transfer into CAFs and competitively adsorb miR-328-5p through the ceRNA mechanism, and regulate the SPON2 expression of CAFs cells, ultimately promote the progression of NSCLC." (PMID 36153414, 2022). "Tumor-derived exosomal HOTAIRM1 can transfer into CAFs and competitively adsorb miR-328-5p, and regulate the SPON2 expression of CAFs cells, ultimately promote the progression of NSCLC." (PMID 36153414, 2022). "Overexpression of SPON2 dramatically accelerated tumor growth and increased tumor weight, while treatment of BLZ945 abolished the effect of SPON2 on tumor growth and invasion." (PMID 34583750, 2021). "Blocking IL10 abrogates the SPON2-mediated intratumoral M2-TAM enrichment into the tumor and tumor growth." (PMID 34583750, 2021). "Functional assays show that SPON2 promotes OS cell proliferation, migration, invasion, and angiogenesis by enhancing the secretion of IL10, CCL2, and CSF1, which leads to M2 macrophage polarization and an immunosuppressive tumor microenvironment." (PMID 40730813, 2025). "The qRT-PCR validation of our findings confirms our microarray observations and found that SPON2 had high expression (approximately 18-fold increase) and MSMB had a moderate overexpression (approximately 2.6-fold increase) in tumor tissues compared to the adjacent normal tissues." (PMID 41200187, 2025).
tumor (continued). "Additionally, compared to the A549 group, Spon2 levels were obviously elevated in A549/DDP cells and in tumor tissues from A549/DDP xenograft mice." (PMID 39731162, 2024). "What’s more, how CAFs interact with tumor cells and the SPON2 regulation mechanism in CAFs have not been thoroughly studied." (PMID 36153414, 2022). "In order to confirm that SPON2 in CAFs is regulated by exosomes rather than other pathways, we cultured tumor cells in culture medium containing GW4869 (a reagent that can inhibit exosome release) and co-cultured them with CAFs for 48 h." (PMID 36153414, 2022). "SPON2 may indirectly induce M2-polarization through upregulating cytokines including IL10, CCL2 and CSF1 expression in tumor cells." (PMID 34583750, 2021). "In addition, overexpression of SPON2 enhanced, while knockdown of SPON2 reduced IL10, CCL2 and CSF1 expression levels and secretion in CRC tumor cells." (PMID 34583750, 2021). "SPON2 participates in activation of immune response and recruitment of inflammatory cells, whereas SPP1 along with other pro-inflammatory factors contributes to tumor growth, angiogenesis by stimulating VEGF and macrophage recruitment." (PMID 33322258, 2020). "The spondin-2 (SPON2) gene is overexpressed in multiple malignant tumors and may promote tumor aggressiveness." (PMID 32952742, 2020). "In contrast, the down-regulation of SPON2 and COL20A1 would exert a tumor-restraining activity." (PMID 32911675, 2020). "Spondin-2 had no prognostic value regarding OS or RFS for patients with larger tumor size and T1/T2 (all P > 0.05)." (PMID 28060752, 2017). "Mechanistically, SPON2 enhances interleukin 10 (IL10), C-C motif chemokine ligand 2 (CCL2), and colony stimulating factor 1 (CSF1) secretion, drives M2 macrophage polarization, and activates the NF-κB/VEGF signaling axis to facilitate EMT and tumor progression." (PMID 40730813, 2025). "Interestingly, SPON2, along with other differently expressed genes in 3 T3 overexpressing PARG, is also a tumor microenvironment regulator, which could indicates this mechanism to underlay the observed effect on 3 T3 derived tumor growth." (PMID 35585513, 2022). "Additionally, overexpression of SPON2 significantly increase the number of tumor-infiltrated M2-TAMs in mice treated with DMSO, while no changes were observed in mice treated with BLZ945." (PMID 34583750, 2021). "We considered that SPON2 on tumor proliferation was not the same in different tumor types." (PMID 32952742, 2020). "Whether tumor cells directly regulate SPON2 expression in CAFs has not been reported." (PMID 36153414, 2022). "Though this study demonstrated preliminary serum reactivity of synthetic SPON2 and MSMB epitopes by ELISA, we did not perform quantitative protein-level validation using standard ELISA kits or immunoblotting, nor did we conduct immunohistochemistry (IHC) on tumor tissues." (PMID 41200187, 2025).
cancer (41 papers, 2012 to 2026). A tumor composed of atypical neoplastic, often pleomorphic cells that invade other tissues. "For instance, the MCPCOUNTER algorithm-based SPON2 expression level in PRAD was inversely connected with the quantity of cancer-associated fibroblast infiltration (Rho = −0.207, P = 2.17e − 05)." (PMID 37713832, 2023). "SPON2 alterations, including mutations, duplications and amplifications, were identified in multiple cancer types." (PMID 37713832, 2023). "Several reports indicated that SPON2 expression might associate with cancer metastasis." (PMID 25945835, 2015). "Preclinical and clinical trials will be essential for evaluating the therapeutic potential of SPON2 inhibition in OS and other cancers with similar TME dynamics." (PMID 40730813, 2025). "Both Spon2 and IGF2BP2 have been implicated in the progression and metastasis of human cancers, including LC." (PMID 39731162, 2024). "The nine genes identified in our signature (Dhx9, Dusp12, Fhl1, Ifitm1, Ndufs1, Pja2, Slc1a3, Soga1, and Spon2) have each been investigated for their role in cancer." (PMID 38193115, 2024). "Recent studies have shown that SPON2 protein is highly expressed in lung cancer, colorectal cancer, liver cancer, and other tumors and is expected to be a new therapeutic target for cancer." (PMID 36959811, 2023). "From the cancer studies, the increased methylation of SPON2 in the sperm of HD patients would result in decreased expression, while the decreased methylation of GDF2 in the sperm of the TC patients would result in increased expression." (PMID 36611168, 2023). "While spondin-2 (SPON2) has been linked to metastasis and cancer advancement, its specific role in bone metastasis within lung ADC patients remains poorly comprehended." (PMID 38260135, 2023). "Positive correlation for SPON2 expression and cancer development, metastasis and invasiveness were shown for different types of tumors, such as ovarian, prostate, colorectal and renal." (PMID 35585513, 2022). "Downstream targets of the T3-integrin ανβ3-MAPK pathway, such as matrix metalloproteinases (MMPs), thrombospondin 1 (TSP-1), and spondin-2, are known to enhance cancer cell migration." (PMID 35008863, 2021). "In recent years, many literatures have reported on the abnormally high expression of MACC1 and SPON2 in various cancers and their potential applications in the development, progression and prognosis of cancer." (PMID 33712897, 2021). "Further, SPON2 levels in eight cancer tissue samples of patients with relapse or metastasis were significantly higher compared with those without relapse or metastasis." (PMID 31691494, 2020). "Furthermore, SPON2 expression may cause a contradictory result in other cancers." (PMID 32492954, 2020). "We first analysed SPON2 expression using the ONCOMINE cancer microarray database, which revealed that SPON2 levels in GC tissues are higher compared with those in para‐tumorous tissues." (PMID 31691494, 2020). "SPON2, a secreted extracellular matrix protein belonging to the F-spondin superfamily, plays multifaceted roles in tumorigenesis and cancer progression." (PMID 28938639, 2017). "These contradictory results suggested that the functional role of SPON2 in cancer metastasis should be further investigated." (PMID 25945835, 2015). "Furthermore, while SPON2 has been shown to play a significant role in OS, its function in other cancers, particularly those with similar immune landscape characteristics, warrants further investigation." (PMID 40730813, 2025). "Therefore, with the considerable upregulation of SPON2 in our study, this supports its recognition as a pan-cancer marker that can be used for diagnosis and potentially targeted therapeutics." (PMID 41200187, 2025). "Therefore, SPON2 exhibits context-dependent roles in cancer, and the heterogeneity of the microenvironment should always be considered." (PMID 38542388, 2024).
cancer (continued). "The Cancer Genome Atlas (TCGA) project and the Gene Expression Omnibus (GEO) database were used in our investigation, which represents the first pan-cancer characterization of SPON2." (PMID 37713832, 2023). "Therefore, we performed a systematic pan-carcinogenic analysis to explore the relationship between Sapiens spondin-2 and cancers." (PMID 37713832, 2023). "Taken together, Many studies have shown that SPON2 may be a latent prognostic biomarker for clinical diagnosis and assessment of cancers." (PMID 37713832, 2023). "MACC1 is directly associated with the regulation of c-MET expression, subsequently inducing EMT via elevated HGF/c-MET signalling, but also of the pluripotency marker NANOG and the cell adhesion factor SPON2, both contributing to cancer progression and metastasis." (PMID 35597866, 2022). "Whether HOTAIRM1 has other biological functions in NSCLC and whether SPON2, as an important cancer-promoting ECM protein, has other regulatory pathways deserve further investigation, and it is now underway in our group." (PMID 36153414, 2022). "However, T3 treatment has been shown to stimulate the overexpression of spondin-2, thereby abrogating the invasion and migration of cancer cells." (PMID 35008863, 2021). "GO analysis of the SPON2-related events has been reported to be involved in cancer development." (PMID 32492954, 2020). "Taken together, these data provide strong evidence that SPON2 expression may be regulated by cancer-induced differential promoter DNA methylation in gastric CAMs, ATMs and NTMs." (PMID 30624614, 2019). "SPON2 is found to be upregulated in many cancers, including CRC." (PMID 30175151, 2018). "Our results revealed the expression of spondin-2 was up-regulation in patients with depth of invasion (T3/T4) and lymph node metastasis (N1-3) indicating higher invasive and metastasizing activity in spondin-2 high-expression cancer cells." (PMID 28060752, 2017). "Spondin-2 is a conserved secreted extracellular matrix protein and a candidate cancer biomarker." (PMID 25945835, 2015). "The expression of SPON2 in human cancers might be modulated by hormones, like thyroid hormone or androgen, as well as by epigenetic mechanism." (PMID 25945835, 2015). "SPON2 expression was induced by the thyroid hormone or androgen in human cancer." (PMID 25945835, 2015). "Consequently, using the TCGA, CPTAC, and GEO datasets, we found the SPON2 gene in distinct cancers." (PMID 37713832, 2023). "It is suggested that SPON2 may play a pro-cancer role in TNBC." (PMID 36959811, 2023). "Blocking the SPON2/integrin β1/PYK2 axis impaired the migration of monocytes and cancer-promoting functions of TAMs in vivo." (PMID 38542388, 2024). "Previous publications already report the transcriptional regulation of cancer- and metastasis-related genes by MACC1 in CRC, like the hepatocyte growth factor receptor c-MET, the adhesion factor SPON2 and the stem-cell transcription factor NANOG." (PMID 35597866, 2022). "Collectively, these results demonstrate that blocking SPON2/integrin β1/PYK2 axis impairs the transendothelial migration of monocytes and cancer-promoting functions of TAMs in vivo." (PMID 34583750, 2021). "Consequently, SPON2 may be a potent target for various cancer progression and immune responses." (PMID 32492954, 2020). "Comparison of the expression level in AEM with the expression level in advanced carcinoma showed that the difference in expression was statistically significant for SPARC and SPON2 (p < 0.001 for SPARC and p = 0.001 for SPON2)." (PMID 33322258, 2020). "Known PCa-related genes (SPON2, TFF3, SPINK1) are among the highest-expressed genes in the “cancer” factor." (PMID 29925878, 2018). "As a transcriptional activator, MACC1 directly regulates the transcription of numerous genes involved in EMT, metastasis, cancer stemness, and drug resistance, including MET, SPON2, and MDR1/ABCB115–18." (PMID 30082743, 2018).
cancer (continued). "The increased SPON2 mRNA expression in CRC was revealed by data mining of eight independent microarray datasets in the Oncomine database, with a total of 654 cancer samples and 178 normal controls analyzed." (PMID 25945835, 2015). "We found also several genes underexpressed in subset of cancer samples like KLK3, FOLH1, SPON2, A2M, and PCP4." (PMID 22811706, 2012). "c-MET and SPON2, as transcriptional targets of MACC1, induced metastasis in xenograft and genetically modified mouse models, and is closely related to the metastasis of cancer patients." (PMID 39695175, 2024). "Furthermore, blocking the SPON2/integrin β1/PYK2 axis impairs the transendothelial migration of monocytes and cancer-promoting functions of TAMs in vivo." (PMID 34583750, 2021). "Furthermore, a subsequent analysis on the possible role of the altered genes in CRC and IPD data sets in the survival of cancer patients (TCGA-COAD data sets) pointed to a significant influence on survival for eight of these genes (TUBB6, PAK6, SULT1A1, SLC11A1, TRAP1, FAM50B, SPON2, FES)." (PMID 34885088, 2021).
cardiovascular disease (3 papers, 2014 to 2025). "In humans, Spondin-2 plasma levels can increase with cardiovascular disease, and Spondin-2 is downregulated in humans with failing hearts." (PMID 39941136, 2025). "We found that in CAD patients with severe stenosis, peripheral blood NK cells expressed higher levels of SPON2, a gene coding for Spondin-2 (Mindin), a secreted extracellular matrix protein, and known to be increase in the plasma of cardiovascular disease patients." (PMID 39941136, 2025). "The increase in SPON2 expression was associated with lower HCMV-induced NK cell frequencies and a relatively higher PBMC TGFβ transcript expression, suggesting a connection to a pro-homeostatic and/or pro-fibrotic state in cardiovascular disease." (PMID 39941136, 2025). "The matricellular protein SPON2 plays diverse roles in the development of cardiovascular diseases." (PMID 32974343, 2020).
infection (3 papers, 2021 to 2025). The state of being infected such as from the introduction of a foreign agent such as serum, vaccine, antigenic substance or organism. "These included cytokines and cytokine receptors (Il11, Tnfsf18, and Ackr4), genes involved in infection (Ptgs2 and Heyl), cell adhesion and migration (Spon2 and Mmp10)." (PMID 35293863, 2022).
degenerative diseases (1 paper, 2021). "These include Spon2, Adam19, Arntl, Cdkn1a, Cry2, Per2, Per3, Wee1, Rcan1, Slc41a3, Errfi1, and Bhlhe41, which are related to numerous cardiovascular and degenerative diseases of other organs as well as varying aging processes." (PMID 33668521, 2021).
SPON2 also shares sentences with these, for which no sentence is quoted: liver cancer (4 papers); pancreatic cancer (3); benign prostatic hyperplasia (2); colon (2); Colorectal (2); lymphoma (2); acute coronary syndrome (1); Adenitis (1); adenocarcinoma (1); angina (1); Barrett adenocarcinoma (1); bone metastasis (1); brain tumour (1); cecum adenocarcinoma (1); Clear Cell Renal Cell Carcinoma (1); colon adenocarcinoma (1); colorectal adenocarcinoma (1); glomerulonephritis (1); glomerulosclerosis (1); heart failure (1); Hepatic fibrosis (1); in situ carcinoma (1); invasive carcinoma (1); kidney disease (1); lymphoid neoplasm (1); measles (1); mesothelioma (1); metastatic disease (1); mucinous adenocarcinoma (1); muscular disease (1).
A further 9 diseases each share a sentence with SPON2 in 1 paper.